ENSG00000200072
Synonyms: LOC124900341
Gene: Small nucleolar RNA gene on chromosome 13 (112,052,078 to 112,052,138, forward strand). Ensembl gene ENSG00000200072.
Gene Ontology:
Biological process: RNA processing
Cellular component: nucleolus
Homologues: Orthologues: rat LOC120097215 (69% identical), mouse Gm23212 (67% identical).